TK1 (thymidine kinase 1)
Diseases named in the same sentence as TK1 in open-access papers (continued):
Sharing a sentence is not in itself a finding about the gene and the disease.
breast carcinoma (continued). "However, in mammary tumor sera, TK1 activity eluted as a major peak with high MW complex, while the TK1 protein eluted in multimeric forms with different MW, representing both active and inactive forms of TK1." (PMID 25881026, 2015). "However, in sera from dogs with mammary tumor only a small portion of active high molecular weight TK1 aggregates were found and a large fraction of apparently inactive TK1 protein." (PMID 26366881, 2015). "The aim was to determine if serum thymidine kinase 1 (sTK1) activity and sTK1 protein levels in dogs with mammary tumors could be useful in veterinary medicine." (PMID 25293656, 2014). "In this study, the use of serum thymidine kinase 1 protein (STK1p) concentration for the prognosis of the overall survival of patients with locally advanced breast cancer (n=51) following routine treatment (neoadjuvant treatment, surgery and chemotherapy) was investigated." (PMID 24649267, 2013). "Although there is a significant correlation between PCNA and TK1 staining of breast cancer tissue, TK1 showed a significant correlation with stage and grade while PCNA did not, indicating that TK1 might be a more accurate marker for diagnosis and prognosis." (PMID 22778736, 2012). "This indicates that TK1 upregulation is an early event in breast carcinoma development, and may be useful in identifying precancerous tissue." (PMID 22778736, 2012). "The present study shows that TK1 can be a potential tumour marker in breast cancer patients." (PMID 19396699, 2009). "The purpose of this study was to investigate the effect of these chemotherapeutic agents on FDG and FLT uptake in human breast cancer cells in vitro and to relate the results with biological parameters, such as TK-1 expression, and activity and cell cycle distribution." (PMID 18665170, 2008). "Additionally, we found that TK1 was overexpressed in colon cancer, clear cell renal cell carcinoma, breast cancer, uterine corpus endometrial carcinoma, lung adenocarcinoma, pancreatic adenocarcinoma, head and neck squamous carcinoma, and hepatocellular carcinoma compared with normal tissue." (PMID 36831773, 2023). "Serum TK1 was subsequently investigated as a tumor marker using monoclonal or polyclonal antibodies against TK1, demonstrating significantly higher levels in preoperative breast cancer patients than in healthy volunteers or patients with benign tumors or following curative surgery for breast cancer." (PMID 29162134, 2017). "Furthermore, breast cancer patients with either high or intermediate TK1 activity in their tumors showed rapid disease progression and poorer prognosis as compared to patients with low TK1 activity in their tumors." (PMID 22778736, 2012). "Similarly, there is a significant correlation between Ki-67 and TK1 in breast cancer tissue when compared to normal tissue; however, due to early upregulation of TK1 as compared with Ki-67, TK1 may be a more accurate prognostic marker." (PMID 22778736, 2012). "Thymidine kinase 1 (TK1) participates in the synthesis of DNA precursor and acts as a biomarker for cancer including prostate and breast cancer, but the specific role of TK1 in the occurrence and development of PCa is unclear." (PMID 36168930, 2022). "For example, genes involved in cell proliferation—such as CDC2, CDC6, and Thymidine kinase 1—are induced by E2 in MCF7 cells, whereas in the similar E2 responsive breast cancer cell line, 231ER+, these same genes are repressed." (PMID 33238524, 2020). "Thymidine kinase 1 (TK1) participates in DNA precursor synthesis and acts as a biomarker for malignant cancer including prostate and breast cancer (Jagarlamudi, Hansson & Eriksson, 2015)." (PMID 32266115, 2020). "Studies have shown that serum TK1 can be used as a monitoring indicator for adjuvant therapy of breast cancer, but whether it can be applied to the clinical efficacy and long-term prognosis assessment of patients with advanced breast cancer with her-2 positive remains to be further studied." (PMID 32202305, 2020).
breast carcinoma (continued). "Sera from 124 breast cancer patients with known TNM classification along with sera from 53 healthy females were analyzed by TK 210 ELISA for TK1 protein and TK1 activity levels by the 3[H]-deoxythymidine (dThd) phosphorylation assay." (PMID 27079872, 2016). "Previously, using systems biology approach and cancer signaling networks, we identified top-5 highly expressed and connected proteins (HSP90AB1, CSNK2B, TK1, YWHAB and VIM) in the invasive MDA-MB-231 breast cancer cell line." (PMID 27527857, 2016). "WalBC cells exhibited expression of known markers of basal invasive human breast cancers as well as increased KRT17, KRT 14 and KRT 19, DSP, s100A4, NDRG-1, ANXA1, TK1 and AQP3 gene expression and decreased gene expression of TIMP3, VIM and TAGLN." (PMID 18179684, 2008). "Notably, an elevated expression of TK1, CDK9, and CD44 within plasma exosomes from drug-resistant breast cancer patients correlates with therapy resistance." (PMID 38001753, 2023). "Although some studies have suggested a potential role of TK1 in tumor development, the effects of increased TK1 expression in breast cancer pathogenesis have not been fully characterized." (PMID 38033034, 2023). "In addition, HOXC-AS3 was also highly expressed in breast cancer tissues, and further researches point out that HOXC-AS3 affected the proliferation of breast cancer cells by targeting thymidine kinase 1 (TK1)." (PMID 36613528, 2022). "Preclinically, we have shown that, among E2F target genes, TK1 was one of the most differentially expressed genes between acquired resistant (PDR) and sensitive (PDS) palbociclib-treated, oestrogen receptor-positive breast cancer cell lines." (PMID 32382111, 2020). "In a retrospective study design, we explored the relationship between serum thymidine kinase 1 (TK1) concentration before radiotherapy and clinical parameters and evaluated the prognostic value of serum TK1 concentration before radiotherapy in breast cancer patients with type 2 diabetes mellitus." (PMID 32202305, 2020). "Overexpression of the thymidine kinase 1 (TK1) and the cyclin-dependent kinase 9 (CDK9) in plasma-derived exosomes was significantly correlated with clinical resistance to CDK4/6 inhibitors in metastatic breast cancer patients." (PMID 32823947, 2020). "Among the listed genes, BIRC5, SEC14L2, Thymidine kinase (TK1), ZNF385B, CLIC6, ELOVL1, CHAF1B and TFF1 have been reported to have a role in early detection of cancers, tumor progression and metastasis in most of cancer types including breast cancer." (PMID 31703592, 2019). "The expression of TK1 on the surface of these solid malignancies seems to mirror that of other surface/stem cell markers such as NCAM in lung cancer, CD133 in lung and colon cancer, and CD298 in breast cancer." (PMID 30214377, 2018). "One possible explanation for the lack of significant serum TK1 response following anastrozole is the relatively significant contribution of serum TK1 activity from noncancer cells in the early-stage breast cancer setting." (PMID 29162134, 2017). "The particular interest in assessing serum TK1 activity in response to CDK4/6 inhibitors stems from the known cell cycle-inhibitory properties of these agents and their importance in the management of patients with advanced HR+ breast cancer." (PMID 29162134, 2017). "However, the study is unique in its ability to obtain concurrent tumor biopsies and serum sample collections for Ki-67 IHC and TK1 activity at serial time points in patients with newly diagnosed, untreated HR+/HER2− breast cancer." (PMID 29162134, 2017). "Different stages of breast carcinoma tissue also stained positive for TK1 including nonspecific infiltrating duct, infiltrating lobular, and infiltrating duct with lymph node metastasis carcinomas." (PMID 22778736, 2012). "Likewise, we confirmed the up-regulation of seven genes (BID, MRRL17, SH3PB5, MRRL49, TK1, TIMM10, and UNG) in rho0 cells and breast cancer cell lines." (PMID 21935467, 2011).
breast carcinoma (continued). "Recent studies indicate that TK1 may be involved in cancer pathogenesis; however, its direct involvement in breast cancer has not been identified." (PMID 38033034, 2023). "Furthermore, the sera from metastasized breast cancer patients had significantly higher levels of TK1 protein and TK1 activity compared to patients without metastasis." (PMID 36201558, 2022). "TK1 has been studied as a prognostic marker and as an early indicator of treatment response in human epidermal growth factor 2 (HER2)-negative early and metastatic breast cancer (BC)." (PMID 38175448, 2024).
lung carcinoma (38 papers, 2012 to 2025). "Recent studies have suggested an association between TK1 and the development of several tumors, including lung cancer, thyroid carcinoma, prostate cancer, and pancreatic cancer." (PMID 36831773, 2023). "A systematic review shows that TK1 overexpression is associated with the poor outcomes of lung cancer patients." (PMID 33711952, 2021). "Fhit−/− mouse kidney cells also expressed trace levels of TK1 compared to Fhit+/+ cells, and stable Fhit knockdown in A549 lung cancer cells caused TK1 down-modulation for at least 9 weeks." (PMID 23209436, 2012). "This study was designed to develop a model of serum thymidine kinase 1 protein (STK1p) concentration in combination with low-dose computed tomography (LDCT) to predict the risk of benign pulmonary nodules progressing into lung cancer within three years in a large screening population." (PMID 38213734, 2024). "We propose that STK1p should be combined with imaging, other biomarkers (e.g., CYFRA21-1, CEA and CTCs) and TK1 immunohistochemically staining, to provide a reliable method for assessment of the development of premalignancy or diseases associated with the risk process of lung cancer." (PMID 33552542, 2020). "The detection of serum TK1 enzyme activity is sensitive and specific enough to predict early-stage and advanced lung cancer." (PMID 39006942, 2024). "HNF4G upregulates the m6A reader, IGF2BP2, by combining with its promoter region, and upregulation of IGF2BP2 enhances the thymidine kinase 1 (TK1) stability and expression, thus facilitating angiogenesis in lung cancer." (PMID 39691597, 2024). "Experimental validation confirmed that thymidine kinase 1 enhances lung cancer invasion, metastasis, and cell cycle progression." (PMID 38761234, 2024). "A clinical study indicates that elevated levels of TK1 in the serum after chemotherapy for lung cancer signify treatment failure and a poorer prognosis." (PMID 38761234, 2024). "The correlation of the four genes HMMR, PFKP, TCN1, and TK1 with tumor-infiltrating immune cells and the survival curve in lung cancer was shown." (PMID 35898471, 2022). "TK1 has been studied as a biomarker for the diagnosis and prognosis of many types of cancer, including lung cancer." (PMID 35190747, 2022). "Spheroids composed of 344SQ murine lung cancer cells with either control or Ube2t-, Tk1-, Cxcl12-, and Kpna2-knockdown CAFs were seeded into collagen gel, and spheroid invasion was then monitored for 2 days." (PMID 35884546, 2022). "For example, TK1 (thymidine kinase 1) integration with CEA, CYFRA21‐1, and NSE achieved a diagnostic accuracy of 0.946 for benign and malignant lung tumors." (PMID 35289087, 2022). "According to another study, membrane expression of TK1 was also found in lung cancer cell lines and cells from breast and colon tumors." (PMID 32317865, 2020). "Some of the pyrimidine metabolic rate–limiting enzymes, such as TK1, UCK2, and RRM1, were reported to be associated with the poor outcomes of lung cancer in systematic review or meta-analysis." (PMID 32638267, 2020). "Similar results were obtained in GSE62948 dataset that the DNA methylation intensity of CAD, RRM2, and TK1 was lower in lung cancer tissues, compared with normal lung tissues." (PMID 32638267, 2020). "Compared with the lung normal tissues, the pyrimidine metabolic rate–limiting enzymes CAD, RRM2, and TK1 were hypo-methylated in lung cancer tissues derived from GSE32867 dataset." (PMID 32638267, 2020). "In patients with lung cancer a high activity of TK1 in serum after the first and second cycles of cytotoxic treatment was associated with a significantly longer survival." (PMID 32423477, 2020). "TK1 is overexpressed in a number of different cancer types, and high levels of TK1 protein have been used as a biomarker for diagnosing and categorizing many types of cancers, including lung cancer." (PMID 31589613, 2019).
lung carcinoma (continued). "Serum detection of TK1 is sensitive and specific for the prediction of early stage and advanced lung cancer." (PMID 32064235, 2019). "Similar results were reported by a study on pT1 lung carcinoma patients, in which TK1 expression, as determined by immunohistochemistry of lung tumor tissues, was correlated with survival." (PMID 24649267, 2013). "Additionally, in esophageal, cardiac, and lung carcinomas, TK1 has been found to be a reliable prognostic factor." (PMID 35311151, 2022). "The application of serum TK1, PCDGF, CYFRA21-1, NSE, and CEA assay plus enhanced CT scan shows high sensitivity and diagnostic accuracy in the diagnosis and chemotherapy monitoring of nonsmall cell lung cancer and thus provides a diagnostic reference basis." (PMID 35368891, 2022). "Similarly, the Kaplan-Meier survival analysis showed that pyrimidine metabolic rate–limiting enzymes DTYMK, NT5C3, RRM1, RRM2, TK1, TYMS, and UCK2 were all associated with adverse prognosis in the lung cancer." (PMID 32638267, 2020). "Overall, these studies indicate that TK1 overexpression might be indicative of a more aggressive form of lung cancer in general, and this protein may have predictive value in LUAD, in particular." (PMID 31589613, 2019). "In addition, growth and differentiation factor 15 was considered to be the main downstream mediator of TK1 function, which induced the metastatic attributes of lung cancer cells." (PMID 32064235, 2019). "Also, TK1 amplification occurred in 2.2% lung cancer patients." (PMID 32638267, 2020). "For instance, in lung cancer, IGF2BP2 increases the stability of fms-related tyrosine kinase 4 (FLT4; also known as VEGFR3) or thymidine kinase 1 (TK1) mRNA, leading to tumor angiogenesis and aggressiveness." (PMID 39098905, 2024). "In lung cancer, the anti-cancer gene miR-320b downregulates the expression of IGF2BP2 and thymidine kinase 1 (TK1), thus suppressing angiogenesis and lung cancer growth." (PMID 35004679, 2021). "And the pyrimidine metabolic rate–limiting enzymes DTYMK, NT5C3, RRM1, RRM2, TK1, TYMS, and UCK2 had particular values in lung cancer prognosis." (PMID 32638267, 2020). "The lack of TK1 hinders the progression of lung cancer by decreasing GDF15 expression and metastatic capabilities." (PMID 39803822, 2025). "Further intersecting these predicted targets with transcriptomic datasets from breast, colorectal, and lung cancers highlighted hub proteins such as TYMS, AURKA, CDK1, and TK-1, which are critical regulators of DNA synthesis, mitotic progression, and cell cycle checkpoints." (PMID 40430485, 2025). "When added to cancer cells expressing mTK1 co-cultured with human MNCs, the anti-TK1-sdAb-IgG1_A1 and D1 were able to elicit a significant antibody-dependent cell-mediated cytotoxicity (ADCC) response against lung cancer cells compared to isotype controls (P<0.0267 and P<0.0265, respectively)." (PMID 35239730, 2022). "Additionally, the use of AK4 gene signatures with sPLS-DA identified the nucleotide salvage gene TK1—another negative prognostic marker of lung cancer —to co-express with AK4, and promote LUAD tumor progression as previously reported." (PMID 34940617, 2021).
prostate carcinoma (20 papers, 2010 to 2025). A carcinoma that arises from epithelial cells of the prostate gland. "The findings of the present study underscored the diagnostic potential of total PSA and TK1 as individual biomarkers for prostate cancer, demonstrating high Area Under the Curve (AUC) values of 0.966 and 0.973, respectively." (PMID 40830177, 2025). "Our study demonstrated a significant association between serum TK1 levels and tumour aggressiveness in prostate cancer, as reflected by Gleason scores and WHO grade groups." (PMID 40830177, 2025). "The findings demonstrated that PSA and TK1, individually and in combination, possess strong diagnostic capabilities, effectively distinguishing between prostate cancer patients and control groups." (PMID 40830177, 2025). "Previously, studies aligned with our findings that TK1 has the potential as a diagnostic biomarker for prostate cancer." (PMID 40830177, 2025). "Higher total PSA, TK1 and FORα were considered independent predictors for prostate cancer susceptibility either in univariate or multivariate analysis." (PMID 40830177, 2025). "This suggests that higher levels of TK1 are associated with an increased likelihood of developing prostate cancer." (PMID 40830177, 2025). "•Measuring TK1 enzyme activity in sEV holds a potential as a diagnostic routine for evaluating prostate cancer aggressiveness." (PMID 39006942, 2024). "This study explores the possible use of monoclonal antibodies for the targeting of membrane associated TK1 in lung, breast, colon and prostate cancer cells." (PMID 32317865, 2020). "Furthermore, our study identified TK1 as a significant independent predictor of prostate cancer susceptibility (OR = 1.213, 95% CI;1.088–1.353)." (PMID 40830177, 2025). "The study also found that higher serum TK1 concentrations at diagnosis were associated with an increased risk of death from prostate cancer, suggesting that serum TK1 levels could serve as a prognostic marker for prostate cancer patients." (PMID 40830177, 2025). "Serum thymidine kinase 1 (sTK1) could be used as a biomarker for risk stratification of patients with metastatic hormone-sensitive or castration-resistant prostate cancers." (PMID 39525979, 2024). "In addition, the antibodies were able to detect multiple forms of TK1 including membrane associated TK1 in lung, breast, colon and prostate cancer cells." (PMID 32317865, 2020). "While the correlation between TK1 activity and protein concentration in sEVs was not explored in this study, the established link between TK1 activity and tumor proliferation potential suggests that investigating this association may offer insights into TK1's diagnostic potential in prostate cancer." (PMID 39006942, 2024). "Thus, we aimed to investigate whether depletion of SNHG4, RRM2, EZH2, AURKA or TK1 can cause prostate cancer cell senescence and affect cell viability." (PMID 37596700, 2023). "In conclusion, this study has significantly contributed to the understanding of the roles played by total PSA, TK1, and FORα as biomarkers in the diagnosis and prognosis of prostate cancer." (PMID 40830177, 2025). "In this study, serum TK1 level was measured in prostate cancer patients and compared with the control group." (PMID 40830177, 2025). "Serum TK1 levels have been proposed as a potential marker for the presence of prostate cancer in a few prior investigations and has been investigated as a monitoring and prognostic marker in leukemia, Hodgkin and non-Hodgkin lymphomas." (PMID 40830177, 2025). "TK1 level was significantly higher in the prostate cancer group with mean value 28.11 ± 4.41pg/ml versus 15.66 ± 5.89 pg/ml in control group (P < 0.001)." (PMID 40830177, 2025).